OCA2 (OCA2 melanosomal transmembrane protein)
Description:
Contributes to a melanosome-specific anion (chloride) current that modulates melanosomal pH for optimal tyrosinase activity required for melanogenesis and the melanosome maturation. One of the components of the mammalian pigmentary system. May serve as a key control point at which ethnic skin color variation is determined. Major determinant of brown and/or blue eye color. Seems to regulate the post-translational processing of tyrosinase, which catalyzes the limiting reaction in melanin synthesis (By similarity).
Synonyms: D15S12; P; BEY; BEY1; BEY2; EYCL; SLC13B1; BOCA; EYCL2; EYCL3; HCL3; PED; SHEP1
Tractability: Antibody: UniProt predicts a signal peptide or a membrane-spanning region; the Human Protein Atlas places it where antibodies can reach.
Gene: Protein-coding gene on chromosome 15 (27,754,874 to 28,099,664, reverse strand). Ensembl gene ENSG00000104044.
Subcellular location: Melanosome membrane
Subcellular location (Human Protein Atlas): Plasma membrane; Cytosol
Pathways (Reactome):
Metabolism: Melanin biosynthesis
Gene Ontology:
Molecular function: chloride channel activity; protein binding; protein-containing complex binding
Biological process: lysosomal lumen pH elevation; melanin biosynthetic process from tyrosine; melanin biosynthetic process; melanocyte differentiation; chloride transmembrane transport; endosome to melanosome transport; transmembrane transport
Cellular component: endoplasmic reticulum membrane; endosome membrane; lysosomal membrane; melanosome membrane; cell surface; melanosome; membrane
Genetic constraint (gnomAD): Loss-of-function variants: 60 observed, 85.6 expected, observed/expected ratio (o/e) 0.7, 90% interval 0.57 to 0.87. The upper end of that interval is the gene's LOEUF score, 0.87, which puts it in group 3 of 6, group 1 being the genes least tolerant of losing a copy. Missense variants: 952 observed, 1,037.2 expected, observed/expected ratio (o/e) 0.92, 90% interval 0.87 to 0.97. Synonymous variants: 406 observed, 427.67 expected, observed/expected ratio (o/e) 0.95, 90% interval 0.87 to 1.03.
Gene-disease validity (ClinGen):
ClinGen rates the evidence that OCA2 causes each of these diseases.
oculocutaneous albinism type 2 (autosomal recessive): Definitive. Oculocutaneous albinism type 2 (OCA2) is a type of OCA and the most common form of OCA seen in the African population, characterized by variable hypopigmentation of the skin and hair, numerous characteristic ocular changes and misrouting of the optic nerves at the chiasm.
Homologues: Orthologues: chimpanzee OCA2 (99% identical), rabbit OCA2 (84% identical), macaque OCA2 (84% identical), dog OCA2 (83% identical), pig OCA2 (81% identical), rat Oca2 (80% identical), mouse Oca2 (78% identical), guinea pig OCA2 (75% identical), tropical clawed frog oca2 (68% identical), zebrafish oca2 (62% identical), Drosophila melanogaster hoe1 (39% identical), Drosophila melanogaster hoe2 (33% identical), and 3 more. Paralogues in human: SLC13A2 (15% identical), SLC13A3 (14% identical), SLC13A5 (13% identical), SLC13A1 (12% identical), SLC13A4 (12% identical).
Diseases named in the same sentence as OCA2 in open-access papers:
OCA2 is named in the same sentence as 211 diseases in open-access papers, as found by Europe PMC text mining. Sharing a sentence is not in itself a finding about the gene and the disease. The quoted sentences say what the papers report.
albinism (72 papers, 2009 to 2026). A congenital disorder characterized by partial or complete absence of melanin pigment in the eyes, hair, or skin. "The identification of a novel variant in the OCA2 gene highlights the importance of genetic counseling for families affected by albinism." (PMID 40735666, 2025). "For example, in Astyanax mexicanus, albinism and depigmentation in cavefish are linked to oculocutaneous albinism type 2 (oca2) and melanocortin receptor 1 (mc1r), respectively." (PMID 40709436, 2025). "Prior studies on A. mexicanus have shown that mutations in oca2 disrupt upstream steps in melanin synthesis, contributing to albinism." (PMID 40709436, 2025). "Pathogenic variants in OCA2 account for ~30% of genetic diagnosis of patients with clinically confirmed albinism." (PMID 40996958, 2025). "The identification of the c.1274T>G; p.Met425Arg variant in the OCA2 gene provides a foundation for the application of advanced reproductive technologies to mitigate the recurrence risk of albinism in future generations." (PMID 40735666, 2025). "The X. hellerii albinism is similar to human oculocutaneous albinism type 2 (OCA2), and inactivation of the OCA2 gene product is known to cause albinism in humans." (PMID 38299666, 2024). "At the same time, we recognize the need to explore strategies to enhance OCA2 expression for treating hypopigmentation disorders associated with loss-of-function OCA2 variants, including albinism." (PMID 39456217, 2024). "Our new finding enriches the database of genetic mutations in OCA2 albinism and will also provide reference value for genetic counseling, accurate diagnosis, and clinicopathological evaluation of this disease." (PMID 38317267, 2024). "We analyzed a case of albinism caused by a mutation in the OCA2 gene by WES technology and identified a de novo mutation site (c.1258G > A), which together with two other mutation sites constitutes a compound heterozygous mutations as the cause of the disease." (PMID 38317267, 2024). "We focus on specific genotypes in the TYR and OCA2 genes; biallelic variants in each of these two genes are associated with albinism, a clinically and genetically heterogeneous group of conditions characterised by reduced levels of melanin pigment." (PMID 39349469, 2024). "This study demonstrates that the co-occurrence of two specific variants in the TYR and OCA2 genes significantly increases the likelihood of having albinism." (PMID 39349469, 2024). "Mutations of Oca2 can result in a form of oculocutanous albinism, which is the most prevalent and visually identifiable form of albinism." (PMID 37431738, 2023). "Distinct coding mutations in oca2 have been identified in two A. mexicanus cave populations, and complementation analysis suggests that regulatory mutations in oca2 cause albinism in a third population." (PMID 39606270, 2023). "The mutant allele of OCA2 is carried in approximately 1 in 70 individuals, categorized as the prevalent type of albinism worldwide, although the frequency of mutation detection is higher in the OCA1 phenotype." (PMID 35741834, 2022). "Average ALs in TYR- and OCA2-associated albinism and in GPR143-associated ocular albinism are similar to those of the reference cohorts in younger patients." (PMID 35704304, 2022). "Some of the proteins thought to regulate melanosomal pH are MATP and OCA2, and mutations in these genes are associated with albinism." (PMID 35406524, 2022). "For example, different mutations in the pigmentation gene oca2 directly lead to albinism in the Molino and Pachón populations." (PMID 35924750, 2022). "The mean AL in individuals with TYR-associated albinism (n = 25; mean AL ± SD, 22.55 ± 2.30 mm) was significantly shorter than for those with OCA2-associated albinism (n = 17; mean AL ± SD, 23.99 ± 1.85 mm) in a simple t-test (P = 0.038)." (PMID 35704304, 2022).
albinism (continued). "Nearly all cases of albinism in African individuals are caused by mutations in the OCA2 gene (previously referred to as the P gene) which maps to the long arm of chromosome 15." (PMID 36353393, 2022). "Significantly increased odds of a longer AL (≥26 mm) were observed for BCM and BED and also (but to a lesser extent) for TYR- and OCA2-associated albinism, as well as for RPE65- and RPGR-associated disease." (PMID 35704304, 2022). "This OCA2 change has previously been suspected to cause albinism in some patients but reports on ClinVar are conflicting." (PMID 31719542, 2019). "Conversely, the genetic basis for albinism in Pachón, Molino and Japonés is the same: a mutated form of oca2." (PMID 29909064, 2018). "As expected, injection of tyr or oca2 sgRNA/Cas9 RNP caused albinism phenotypes in almost all cases." (PMID 29358165, 2018). "In the Mexican cavefish Astyanax mexicanus, albinism was a result of loss of function deletions in the oca2 gene that functions in the first step of melanin synthesis." (PMID 29215078, 2017). "Loss of oca2 results in albinism in a number of species (for example), and oca2 lies under the QTL peak for albinism in crosses between surface and albino cave Astyanax mexicanus." (PMID 25774757, 2015). "One of the most common forms of albinism is caused by mutations in a highly conserved protein encoded by the oculocutaneous albinism II gene (OCA2)." (PMID 25513726, 2014). "The most common type of albinism is caused by defects in a protein called OCA2, which is found in the membrane that surrounds melanosomes." (PMID 25513726, 2014). "In albino cavefish, mutations in oca2, the homologue of the mouse pink eyed dilution or p gene, are the cause of albinism." (PMID 24282555, 2013). "For instance, albinism was mapped to Oca2 in two separate populations of cavefish, Astyanax mexicanus, whereas a complementation cross in a third population indicated that albinism arose through mutations in the same gene." (PMID 23075840, 2012). "A significant overlap in the range of phenotypes in individuals with TYR (OCA1) and OCA2 mutations was found, which makes genetic screening obligatory for the diagnosis of the type of albinism of the affected individuals." (PMID 22734612, 2012). "A liberal estimation of the allele frequency for any OCA2 sequence variations in albinism patients at about 25% is supported by the literature." (PMID 21541274, 2011). "Mutations in OCA2 are responsible for the most common form of albinism, oculocutaneous albinism type 2 and several studies have shown this gene to be associated with common skin, hair and eye color variation found in European populations." (PMID 19772629, 2009). "Overall, the modulation of OCA2 exon 10 skipping by both benign and pathogenic variants provides a basis for improving the genetic diagnosis of albinism, and paves the way for research into the molecular and evolutionary mechanisms behind human pigmentation diversity." (PMID 40996958, 2025). "Although the characterization of the molecular mechanism is pending, studies of albinism in X. hellerii yielded the same gene underlying the human oculocutaneous albinism, i.e. Xiphophorus oca2 and human OCA2, providing another example of the construct validity of this model." (PMID 38299666, 2024). "To note, the R305W variant of OCA2, which is associated with eye and skin color, was detected in eight of 17 patients, while the L374F variant, which affects pigmentation, was present in all albinism patients studied." (PMID 38279271, 2024). "However, this variant was found in trans of the pathogenic or likely pathogenic OCA2 variant c.1031T>C;p.(Leu344Pro) in several patients addressed for albinism diagnosis to our laboratory (unpublished results)." (PMID 39201349, 2024). "Oca2 is a membrane transporter of tyrosine for melanin synthesis, and the oca2 variant-driven albinism in X. hellerii could depend on either oca2 mutation and/or aberrant expression." (PMID 38299666, 2024).
albinism (continued). "For example, for oca2, a gene associated with albinism and where a knock-out has already been established in A. calliptera, oca2 could be replaced with GFP." (PMID 38018094, 2023). "Also, albeit with a lower effect size, both TYR- and OCA2-associated albinism had significantly higher odds of longer ALs." (PMID 35704304, 2022). "Oca2 plays a role in melanin synthesis and eye color determination and has been linked to albinism." (PMID 34794440, 2021). "In the case of the OCA2 A481T and N489D variants, both of which have been observed among individuals with albinism, the predicted large change in folding free energy can be attributed to the change in the physicochemical properties of the wild-type residues: A→T and N→D." (PMID 34361043, 2021). "Other albinism classes are: OCA2 caused by deletion or loss of activity of the melanosomal P-protein (OCA2 gene); OCA3 attributable to mutations in TYRP1; OCA4 due to loss of SLC45A2; and OCA5 which is linked to chromosome 4q24, with the responsible gene yet to be characterized." (PMID 32966289, 2020). "Indeed, two Mendelian pigment phenotypes (albinism and brown) are both widespread, highly penetrant, and mediated through loss-of-function mutations in the genes Oca2 and Mc1r, respectively." (PMID 27363593, 2016). "Whereas the absence of melanin is traditionally considered as one character state, albinism, irrespective of the underlying genetic basis, we propose here to distinguish OCA2-associated albinism from Mc1R-associated albinism, or from albinism associated with any other gene." (PMID 26042146, 2015). "The most common form of albinism is caused by mutations in oculocutaneous albinism II (OCA2), a melanosome-specific transmembrane protein with unknown function." (PMID 25513726, 2014). "These experiments reveal a potential evolutionary benefit of albinism caused by oca2 loss of function in cavefish: enhancement of the alternative CAT pathway to promote multiple physiological and/or behavioral functions that are adaptive for survival in the extreme cave environment." (PMID 24282555, 2013). "In Astyanax mexicanus, which has a pigmented surface dwelling form (surface fish) and several albino cave-dwelling forms (cavefish), albinism is caused by loss of function mutations in the oca2 gene, which operates during the first step of the melanin synthesis pathway." (PMID 24282555, 2013). "To investigate the possible relationship between the enhanced CAT synthesis pathway and the blocked melanin pathway in cavefish, we examined the embryonic expression pattern of the oca2 gene, whose loss of function has been identified to be the cause of cavefish albinism." (PMID 24282555, 2013). "However, GRM5 and APBA2 lie 396 kb upstream and 1025 kb upstream of TYR and OCA2, respectively, two well-known pigmentary genes for which a complete loss-of-function causes albinism in humans and in other animals." (PMID 23555287, 2013). "The results of our survey demonstrate that the detected novel N687S TPC2 variant alone cannot be regarded pathogenic in albinism; however, we cannot exclude the possibility that in combination with trans variants such as the R305W of the OCA2 protein, it could influence pigmentation." (PMID 38279271, 2024). "These experiments also support the hypothesis that loss-of-function oca2 alleles in cavefish cause albinism in these fish, consistent with QTL mapping, the inability of cavefish alleles to rescue pigmentation in mammalian cell culture, and morpholino knockdown in surface fish." (PMID 25774757, 2015). "Albinism disrupts the tyrosine-to-melanin biochemical pathway due to mutations in genes such as TYR, OA1, and OCA2." (PMID 40125119, 2025). "This study underscores the importance of genetic analysis in characterizing OCA2 variants and highlights the need for further exploration of molecular mechanisms and phenotypic variability in OCA2-related albinism to improve diagnosis and counseling." (PMID 40735666, 2025).
albinism (continued). "Many of these loci encompass variants previously linked to retinal layer thickness parameters (including TSPAN10 and LINC00461) while a subset of them has been linked to monogenic disorders, most notably, albinism (including TYR, OCA2 and GPR143)." (PMID 40666342, 2025). "Including c.1065G > A in genetic testing not only applies to OCA2 patients with missing heritability but also to patients with other types of albinism taking into account epistasis of OCA2 on downstream genes." (PMID 40996958, 2025). "A molecular epidemiological survey of 179 patients with albinism by Chinese scholars showed that OCA2 accounts for 11.7% of albinism in China." (PMID 40313672, 2025). "Among these, the OCA2 gene is exclusively responsible for OCA type 2 (OCA2), which is one of the most prevalent forms of albinism worldwide." (PMID 40735666, 2025). "In the total study population, four common variants of known albinism genes were detected with high frequencies: the L374F variant of the SLC45A2 protein, the R305W of the OCA2 protein and the R402Q and S192Y TYR proteins." (PMID 38279271, 2024). "Molecular genetic diagnosis for most patients started with a next-generation sequencing (NGS) panel targeting genes associated with albinism—TYR, OCA2, MC1R, MITF, SLC45A2, TYRP1, and GPR143—as the initial clinical diagnosis for all patients was albinism." (PMID 39457042, 2024). "A multicentre study of 907 patients with FH found that 67% of individuals had albinism caused by variants in GPR143, OCA2, TYR and HPS1 genes, followed by 21.8% with PAX6, 6.8% with SLC38A8 and 3.5% with FRMD7 variants." (PMID 37762234, 2023). "The most common causative genes in non-syndromic OCA are TYR and OCA2 and HSP1 is in the syndromic albinism." (PMID 35328057, 2022). "OCA2 is the second most investigated albinism type due to the defective OCA2 gene (MIM# 203200) that was earlier reported as the P gene." (PMID 35741834, 2022). "OCA1 accounts for half of all albinism cases, while OCA2 accounts for 30% of cases, and zebrafish models exist for both of these conditions." (PMID 35406524, 2022). "Molecular studies identified seven genes linked to the OCA phenotype (TYR, OCA2, TYRP1, SLC45A2, SLC24A5, C10orf11, and DCT) and one locus (OCA5) in consanguineous and sporadic albinism." (PMID 35741834, 2022). "Several studies reported the genetic mutations in OCA1, OCA2, OCA3, OCA4, and OCA6 albinism in Pakistani families." (PMID 35741834, 2022). "We further functionally verified that a change in the oca2 locus is responsible for albinism in the F2 hybrids, by crossing an albino surface/Pachón F2 hybrid with a genetically engineered surface fish heterozygous for a deletion in oca2 exon 2127." (PMID 33664263, 2021). "This study assessed previously reported coding variants in albinism genes (TYR, OCA2, TYRP1, SLC45A2, SLC24A5, LRMDA) and common intronic, regulatory variants of OCA2 in individuals with amelanotic/hypomelanotic melanoma, pigmented melanoma cases and controls." (PMID 32966289, 2020). "The genes identified for MAC were KMT2D, MAB2IL2, ALDH1A3; ASDA were KERA, PAX6, MYOC, TGFBI, and SLC4A11; congenital cataract were CRYBB2, EPHA2, HSF4 and BCOR; infantile nystagmus were CACNA1A and FRMD7; and albinism were OCA2, GPR143, HPS6 and SLC38A8." (PMID 32830442, 2020). "A notable finding for patients with query albinism and infantile nystagmus, was that a number of genes were found in both subgroups, including OCA2 and SLC38A8." (PMID 32830442, 2020). "Findings in a small but significant minority of individuals with partial albinism suggest that investigating the penetrance of TYR variants and exploring a digenic inheritance model involving TYR and OCA2 would be of interest." (PMID 31719542, 2019). "Of the six different mutations found in OCA2; N465D8, V419I, Y342C35 and L650V36 have been reported previously in association with albinism." (PMID 28667292, 2017).